SPON2 (spondin 2)
Diseases named in the same sentence as SPON2 in open-access papers (continued):
Sharing a sentence is not in itself a finding about the gene and the disease.
gastric cancer (continued). "As a result, SPON2 is expected to play a significant role in gastric cancer development with inflammation and H. pylori infection." (PMID 32492954, 2020). "Further, we observed the effect of SPON2 overexpression on gastric cancer cell proliferation and cell motility." (PMID 32492954, 2020). "SPON2 expression level was confirmed by reverse transcription polymerase chain reaction (RT-PCR) in normal gastric epithelial cell line and seven gastric cancer cell lines." (PMID 32492954, 2020). "Results showed that overexpression of SPON2 promotes cell proliferation, migration, and invasion in gastric cancer cells." (PMID 32492954, 2020). "Data showed that the majority of the gastric cancer cell lines had high SPON2 expression levels compared to GES-1 normal gastric epithelial cells." (PMID 32492954, 2020). "We selected three GEO datasets, which showed that SPON2 expression level is increased in patients with gastric cancer." (PMID 32492954, 2020). "Overall, these results suggest SPON2 as a potential therapeutic target for impeding gastric cancer progression, which can be regulated by Notch signaling inhibition." (PMID 32492954, 2020). "At first, we investigated the expression level of SPON2 in patients with gastric cancer using publicly available data." (PMID 32492954, 2020). "To further explore the significance of spondin-2 expression on aggressiveness in gastric cancer, we firstly discussed the relationship of spondin-2 expression with depth invasion and lymph node metastasis." (PMID 28060752, 2017). "To elucidate the functions of Spondin-2 in gastric cancer, we analyzed spondin-2 status in 174 gastric cancer specimens with other widely recognized clinicopathologic parameters." (PMID 28060752, 2017). "In the present study, the expression of spondin-2 was investigated in 174 gastric carcinoma samples by IHC." (PMID 28060752, 2017). "The concentration of SPON2 in the plasma of gastric cancer patients were low comparing with that of CRC patients, but was also higher than that of the healthy individuals." (PMID 25945835, 2015). "SPON2 overexpression in gastric cancer and triple negative breast cancer is reported to be associated with tumorigenicity and aggressive clinical characteristics and poorer outcomes, suggesting it may have a role in malignant progression and metastasis." (PMID 41200187, 2025). "In summary, SPON2 plays a carcinogenic role in the development of gastric cancer and may be used as a marker for gastric cancer diagnosis and a new therapeutic target for gastric cancer." (PMID 37713832, 2023). "SPON2 promotes the proliferation, migration, and invasion of gastric cancer cells." (PMID 36959811, 2023). "Moreover, it was demonstrated that the MACC1 target SPON2 can also induce ERK activation in gastric cancer cells." (PMID 37051546, 2023). "Moreover, knockdown of SPON2 was observed to inhibit the migratory and invasive abilities of gastric cancer cells as revealed by trans-well cell migration and invasion assay." (PMID 32492954, 2020). "Therefore, we focused on the role of SPON2 in gastric cancer progression and investigated the mechanism of SPON2 expression using in vitro and in vivo experiments, and public databases on patients with gastric cancer." (PMID 32492954, 2020). "Furthermore, SPON2 in combination with Notch signaling inhibitor can provide a potential therapeutic strategy to target gastric cancer." (PMID 32492954, 2020). "In conclusion, we demonstrated that SPON2 is an important regulator of gastric cancer progression." (PMID 32492954, 2020). "Thus, SPON2 has been reported to be differentially expressed in various carcinomas and contributes to poor prognosis of diverse cancers including gastric cancer." (PMID 32492954, 2020). "Thus, we further confirmed SPON2 expression in gastric cancer cell lines and performed a cDNA microarray analysis." (PMID 32492954, 2020).
gastric cancer (continued). "Therefore, the role of Notch signaling pathway-regulated SPON2 is additional evidence related to metastasis and is important in gastric cancer progression." (PMID 32492954, 2020). "Therefore, this study suggests the role of SPON2 as a down-stream target of Notch signaling pathway in gastric cancer progression and motility; we also showed the regulation mechanism of Notch signaling and SPON2 in gastric cancer." (PMID 32492954, 2020). "Subsequently, we focused on regulatory mechanism of SPON2 in gastric cancer." (PMID 32492954, 2020). "Furthermore, to investigate SPON2 expression in human gastric cancer tissues, we performed immunohistochemical staining on commercialized tissue microarrays (TMAs)." (PMID 32492954, 2020). "In this article, we proposed a hypothesis that correlates SPON2 expression with the progression and prognosis of gastric cancer and its regulatory mechanisms." (PMID 32492954, 2020). "In addition, SPON2 expression was observed to be regulated by Notch signaling inhibitor (GSI) in gastric cancer." (PMID 32492954, 2020). "In this study, we aimed to elucidate the role of SPON2 in gastric cancer progression." (PMID 32492954, 2020). "Overall, this article proposes that SPON2 is a potent target to improve gastric cancer progression." (PMID 32492954, 2020). "However, the mechanism regulating SPON2 expression needs to be investigated as its role in gastric cancer remains obscure." (PMID 32492954, 2020). "Our findings and previous observations strongly suggest that spondin-2 overexpression is involved in the tumor progression and may work as a prognostic factor for gastric cancer patients." (PMID 28060752, 2017). "In summary, we proved that overexpression of spondin-2 may have positive role in tumor invasion, lymph node metastasis and prognosis, and could be a promising biomarker for prognostic prediction in gastric cancer." (PMID 28060752, 2017). "Furthermore, the patients with high Spondin-2 expression was a poor independent predictor for OS in gastric cancer patients (HR = 1.747, 95% CI: 1.178-2.591; P = 0.006)." (PMID 28060752, 2017). "Furthermore, the multivariate Cox model analysis indicated that spondin-2 up-regulation was an independent factor for poor RFS as well as OS in gastric cancer." (PMID 28060752, 2017). "Collectively, spondin-2 expression in gastric cancer promoting tumor progression indicates that spondin-2 could be a feasible target in cancer therapy." (PMID 28060752, 2017). "In addition, overexpression of spondin-2 was significantly associated with well differentiation, depth of invasion, lymph node metastasis, and advanced TNM stages in gastric cancer." (PMID 28060752, 2017). "Notably, the association of spondin-2 expression with prominent serosal invasion and lymph node metastasis positivity suggested a potential role of spondin-2 in increased invasion and metastasis of gastric cancer." (PMID 28060752, 2017). "In conclusion, Spondin-2 overexpression contributes to tumor aggressiveness and prognosis, and could be a promising target for prognostic prediction in gastric cancer patients." (PMID 28060752, 2017). "Furthermore, SPON2 was shown to inhibit E-cadherin and N-cadherin in gastric cancer." (PMID 37051546, 2023). "In addition, spondin-2 was positively correlated with MMP-9 among 174 gastric cancer samples." (PMID 28060752, 2017). "However, the role of Spondin-2 expression on the prognosis of patients with gastric cancer remains unclear." (PMID 28060752, 2017). "In addition, spondin-2 was positively correlated with MMP-9 protein expression in gastric cancer." (PMID 28060752, 2017). "Among gastric cancer cell lines, we selected AGS and SNU-668 cells (having relatively low SPON2 expression) and MKN28 and SNU-601 cells (having relatively high SPON2 expression) for subsequent experiments." (PMID 32492954, 2020). "However, the mechanism by which SPON2 plays a role in gastric cancer is unknown." (PMID 32492954, 2020).
gastric cancer (continued). "The relationship between the expression of spondin-2 and MMP-9, clinicopathological/prognostic value in gastric cancer was examined." (PMID 28060752, 2017). "To further confirm the effect of Spondin-2 status on RFS and OS in gastric cancer, we firstly performed univariate analysis of traditional clinicopathologic parameters for prognosis." (PMID 28060752, 2017). "Spondin-2 and matrix metallopeptidase 9 (MMP-9) expression was detected by immunohistochemistry in 174 gastric carcinoma tissues." (PMID 28060752, 2017). "Additionally, we confirmed the basal expression level of SPON2, RBP-Jk, and N1ICD in seven gastric cancer cell lines." (PMID 32492954, 2020). "Therefore, we also evaluated the correlation of Spondin-2 and MMP-9 expression in gastric cancer patients and found that Spondin-2 was positively correlated with MMP-9 expression in 174 gastric carcinoma tissues (r = 0.575, P < 0.001)." (PMID 28060752, 2017). "The expression of Spondin-2 in gastric cancer tissue is higher than that in adjacent non-tumorous tissues." (PMID 28060752, 2017). "We found that spondin-2 was up-regulated in gastric cancer tissues compared with adjacent non-tumorous tissues." (PMID 28060752, 2017). "To investigate the biological significance of Spondin-2 in gastric cancer, we detected the expression of Spondin-2 in 174 gastric cancer tissues (tumor and matched adjacent non-tumorous tissues) by immunohistochemistry." (PMID 28060752, 2017). "Overexpression of Spondin-2 was observed in 87 of 174 (50.0%) of gastric cancer samples, compared with 34/174 (19.5%) in adjacent non-tumorous tissues (P < 0.001)." (PMID 28060752, 2017). "The results suggested that Spondin-2 expression was significantly higher in gastric cancer than that in adjacent non-tumorous tissues." (PMID 28060752, 2017). "Spondin-2 was significantly higher in gastric cancer than that in adjacent non-tumorous tissues." (PMID 28060752, 2017). "However, the role of spondin-2 in gastric cancer has not been thoroughly elucidated." (PMID 28060752, 2017).
hepatocellular carcinoma (13 papers, 2015 to 2025). A malignant tumor that arises from hepatocytes. "The distinct effect of SPON2 on metastasis in hepatocellular carcinoma and in CRC is probably due to the discrepancy in macrophage infiltration in the two types of tumors." (PMID 34583750, 2021). "In hepatocellular carcinoma, SPON2 promotes M1-like macrophage recruitment and inhibits tumor metastasis." (PMID 34583750, 2021). "In contrast to our findings, SPON2 not only promotes infiltration of M1-like macrophages but also inhibits tumor cell migration and tumor metastasis in hepatocellular carcinoma." (PMID 34583750, 2021). "While SPON2 knockdown cell lines exhibit higher hepatoma cell migration and invasion, overexpression repressed them." (PMID 34445986, 2021). "The distinct effect of SPON2 on metastasis in hepatocellular carcinoma and in CRC is probably due to the discrepancy in the cell biology and TME in the two types of malignancies." (PMID 34583750, 2021). "SPON2 has also been shown to recruit M1-like macrophage and inhibit hepatocellular carcinoma; however, the expression levels were observed to increase in malignant hepatocellular carcinoma." (PMID 32492954, 2020). "SPON2 can enhance M1-like macrophage recruitment to repress hepatocellular carcinoma by regulating RhoA pathways." (PMID 33552977, 2020). "For example, SPON2 promotes the infiltration of M1‐like macrophages by affecting the activity of the RhoA‐Rho kinase signalling pathway, further inhibiting hepatocellular carcinoma (HCC) cells from invading adjacent tissues and migrating to distant sites." (PMID 31691494, 2020). "Although SPON2 protein was upregulated in hepatocellular cancer cell, in vitro assay indicated that SPON2 expression was negatively affected cell invasiveness and migration." (PMID 25945835, 2015). "In hepatocellular carcinoma, SPON2 is also upregulated compare to non-transformed tissue, but interestingly, patients with high SPON2 expression have a better overall survival rate." (PMID 35585513, 2022). "Since SPON2 regulates Rho GTPase expression in DCs by interacting with the integrins α4β1 and α5β1, different expression and activity of integrins in CRC and hepatocellular carcinoma may also contribute to the functional contradiction." (PMID 34583750, 2021).
colon cancer (10 papers, 2015 to 2023). "Overexpression of Spon2 is highly associated with colon cancer metastasis, which displays one of the most feared side effects of CRC." (PMID 35457963, 2022). "Our analysis suggested that SPON2 could be an independent diagnostic and prognostic biomarker of colon cancer." (PMID 25945835, 2015). "Spondin-2 could be an independent diagnostic and prognostic biomarker of colon cancer." (PMID 25945835, 2015). "Moreover, spondin-2 could be an independent diagnostic and prognostic biomarker of colon cancer." (PMID 28060752, 2017). "Tissue staining of epithelial-specific COL3A1 expression had a superior prediction value of AUC 0.975 and the highest sensitivity/specificity of 95.2%/91.1%, which was comparable to spondin-2, another molecular marker of colon cancer." (PMID 26741506, 2016). "It should be noted that these analyses, which showed a consistent upregulation of SPON2 in colon cancers, were performed independently and contained a total of 654 cancer cases and 178 normal controls." (PMID 25945835, 2015). "We performed ectopic expression of SPON2 in colon cancer cell lines and found that the upregulated SPON2 induced an accelerated proliferation of the cells." (PMID 25945835, 2015). "Western blot analysis of SPON2 expression indicated that SPON2 was abundant in colon cancer cell lines HT-29, LoVo and Caco-2, but low in HCT-116, SW-480 and SW-620." (PMID 25945835, 2015). "We analyzed the differential expression of SPON2 mRNA between colon cancer tissues and normal colonic tissues by data-mining of the Oncomine microarray gene expression datasets." (PMID 25945835, 2015). "To address the protein change of SPON2 in colon cancer tissues, we performed IHC analyses of SPON2 expression using two commercial independent TMAs, each of which contains 90 cases of colorectal adenocarcinoma." (PMID 25945835, 2015). "To get further insight into the functional role of SPON2 in tumorigenesis of colon cancer, we performed in vitro proliferation assays using colon cancer cell lines." (PMID 25945835, 2015). "The relationship of SPON2 expression with clinicopathological parameters of colon cancer was less addressed." (PMID 25945835, 2015). "The Western blot assay indicated that FLNC, COL6A3, COL4A1 and SPON2 were abundantly expressed in the colonic fibroblasts instead of the colon cancer epithelial cells." (PMID 26338966, 2015). "Despite above findings, the relationships of SPON2 mRNA and protein overexpression with clinicopathological parameters and prognosis of colon cancer remain further explorations." (PMID 25945835, 2015). "The protein expression of SPON2 in the colon cancer cell lines and plasma of CRC patients were analyzed using Western blot and enzyme-linked immunosorbent assay (ELISA), respectively." (PMID 25945835, 2015). "However, some studies have shown that SPON2 suppresses colon cancer by blocking angiogenesis." (PMID 32492954, 2020). "The higher the plasma concentration of SPON2, the more likely that it might be a colon cancer." (PMID 25945835, 2015). "Furthermore, ectopic expression of Spondin-2 enhanced colon cancer cell proliferation." (PMID 25945835, 2015). "We discovered a connection between high SPON2 expression and a poor DFS prognosis for colon cancer (P = .011)." (PMID 37713832, 2023). "We chose COL4A1, COL6A3, spondin-2 (SPON2) and FLNC for further analysis for their high abundance (peptide count), high “fold change” and less chances being identified in colon cancer cell lines." (PMID 26338966, 2015). "In current study, we analyzed SPON2 expression in colon cancer cell lines, CRC clinical tissues and CRC plasma samples and revealed that SPON2 mRNA and protein were upregulated significantly in CRC specimens comparing with normal colonic samples." (PMID 25945835, 2015). "In current study, no significant change of colon cancer cells in migration was observed when SPON2 was overexpressed." (PMID 25945835, 2015).
ovarian carcinoma (9 papers, 2008 to 2021). A malignant neoplasm originating from the surface ovarian epithelium. "In addition, SPON2 is used as a diagnostic biomarker for prostate and ovarian cancers through its detection in the patient's blood." (PMID 28938639, 2017). "We also included the novel cancer markers B7-H4, regenerating protein IV (Reg-IV) and Spondin-2, which have been reported to be differentially expressed in ovarian cancer." (PMID 18766180, 2008). "It has also been proved that B7-H4, SPON2, and DcR3 are potential biomarkers that might improve early detection of ovarian cancer." (PMID 28938639, 2017). "SPON2 has been raised as a potential clinical biomarker for prostate and ovarian cancer." (PMID 25945835, 2015). "Iris Simon discovered that SPON2 is up-regulated in sera of ovarian cancer patients." (PMID 22615945, 2012). "Sera from ovarian cancer patients were collected prior and during chemotherapy and were analysed by enzyme-linked immunosorbent assay for CA125, kallikreins 5, 6, 7, 8, 10 and 11, B7-H4, regenerating protein IV and Spondin-2." (PMID 18766180, 2008). "The clinical applicability of the other three candidate ovarian cancer markers included in this study, B7-H4, Reg-IV and Spondin-2, is still unknown." (PMID 18766180, 2008). "For example, CA125, KLKs 5, 6, 10, B7-H4 and Spondin-2 baseline values (c0) predicted a worse overall survival and CA125, KLKs 5, 6, 10, 11, B7-H4 and Spondin-2 baseline values (c0) a worse progression-free survival of ovarian cancer patients." (PMID 18766180, 2008).
lung carcinoma (7 papers, 2005 to 2024). "SPON2 upregulation, which is linked to its promoter hypomethylation, was associated with enhanced bone metastasis in prostate and lung cancers." (PMID 39796635, 2024). "The ECM protein mindin has been shown to be expressed in primary lung cancers, and its homolog in humans, Spondin 2, is a prostate‐associated protein." (PMID 32614521, 2020). "In lung cancer cell lines, SPON2 was found to be overexpressed compared with that in normal lung cell lines in vitro." (PMID 28938639, 2017). "SPON2 was originally isolated as a gene downregulated in lung cancer cell lines compared to normal lung." (PMID 15583692, 2005). "Interestingly, it’s contradictory to results of other previous reports that lung cancer cells do not express SPON2, which attracts our interest." (PMID 36153414, 2022).
breast carcinoma (6 papers, 2015 to 2025). "Genes that are attenuated with SP receptor antagonism, such as SPON2, are involved in cancer progression and metastasis of many tumors other than breast cancer." (PMID 34359773, 2021). "SPON2 mRNA was found to be upregulated in metastatic lymph node tumors comparing with primary breast cancer, as well as in invasive carcinoma comparing with in situ carcinoma of breast cancer." (PMID 25945835, 2015). "Using an engineered metastatic niche, we identified a 9‐gene signature (Dhx9, Dusp12, Fhl1, Ifitm1, Ndufs1, Pja2, Slc1a3, Soga1, Spon2) that successfully delineated metastatic breast cancer from nonmetastatic breast cancers including an invasive cell line without metastatic potential." (PMID 38193115, 2024). "​The expression of SPON2 mRNA was detected by qPCR in TNBC cells MDA-MB-231, non-TNBC breast cancer cells MCF-7, and normal breast cells MCF-10A." (PMID 36959811, 2023).